FAM177B (family with sequence similarity 177 member B)
Synonyms: RP11-452F19.2; FLJ43505
Tractability: No criterion of Open Targets' tractability assessment is met for any kind of drug.
Gene: Protein-coding gene on chromosome 1 (222,737,202 to 222,753,157, forward strand). Ensembl gene ENSG00000197520.
Subcellular location (Human Protein Atlas): Mid piece
Genetic constraint (gnomAD): Loss-of-function variants: 8 observed, 7.59 expected, observed/expected ratio (o/e) 1.05, 90% interval 0.61 to 1.77. That is too few expected variants to judge how well the gene tolerates losing a copy. Missense variants: 115 observed, 122.2 expected, observed/expected ratio (o/e) 0.94, 90% interval 0.81 to 1.1. Synonymous variants: 39 observed, 41.51 expected, observed/expected ratio (o/e) 0.94, 90% interval 0.73 to 1.23.
Homologues: Orthologues: chimpanzee FAM177B (96% identical), macaque FAM177B (92% identical), pig FAM177B (73% identical), dog FAM177B (62% identical), tropical clawed frog galnt11 (41% identical), Drosophila melanogaster CG8300 (23% identical). Paralogues in human: FAM177A1 (35% identical).
Diseases named in the same sentence as FAM177B in open-access papers:
FAM177B is named in the same sentence as 6 diseases in open-access papers, as found by Europe PMC text mining. Sharing a sentence is not in itself a finding about the gene and the disease. The quoted sentences say what the papers report.
coronary artery disease (2 papers, 2023 to 2024). "FAM177B was identified as being associated with coronary artery disease and myocardial infarction." (PMID 39526184, 2024). "The top upregulated gene in the HCM LA was FAM177B, which is a suspected M1 macrophage marker and has been recently identified as a candidate gene for coronary artery disease." (PMID 36928240, 2023).
epilepsy (1 paper, 2025). A brain disorder characterized by episodes of abnormally increased neuronal discharge resulting in transient episodes of sensory or motor neurological dysfunction, or psychic dysfunction. "KCNV2 is known as a marker for severe epilepsy and FAM177B is known to be exclusively expressed in microglia." (PMID 40331981, 2025).
FAM177B also shares sentences with these, for which no sentence is quoted: cognitive deficits (1 paper); myocardial infarction (1); sarcopenia (1); tumor (1).